CX3CL1 (C-X3-C motif chemokine ligand 1)
Diseases named in the same sentence as CX3CL1 in open-access papers (continued):
Sharing a sentence is not in itself a finding about the gene and the disease.
nephritis (1 paper, 2025). Inflammation of renal tissue. "The anti-Thy1 nephritis model was established as the MsPGN model to determine the regulation of CX3CL1 and CX3CR1 during the development of disease." (PMID 40458609, 2025). "Here, we determined that CX3CL1 expression in mesangial cells and CX3CR1+ monocyte/macrophage infiltration in glomerulus was up-regulated and was associated with glomerulus regional immune injury in clinical specimen and anti-Thy1 nephritis." (PMID 40458609, 2025).
nerve sheath tumors (1 paper, 2024). "The link of CXCL12 and CX3CL1 expression to human nerve sheath tumors has also been reported in recent literature." (PMID 40115159, 2024).
non-alcoholic steatohepatitis (1 paper, 2023). "There is evidence that the interaction of CX3CL1 with its specific receptor CX3CR1 is involved in the development of non-alcoholic steatohepatitis and in the process of skin wound healing through chemotactic recruitment of macrophages and regulation of their migration and polarization." (PMID 38283363, 2023).
ovarian serous cystadenocarcinoma (1 paper, 2023). A malignant serous cystic epithelial neoplasm arising from the ovary. "The data indicated that CX3CL1, across a variety of cancer types, was substantially associated with distinct pathological stages, including KICH, KIRC, ovarian serous cystadenocarcinoma (OV), LUSC, STAD, and LIHC." (PMID 37153002, 2023).
ovarian tumor (1 paper, 2011). "Finally, our data are consistent with a model in which GILZ activates CX3CL1 and the chemokine acts alone to support ovarian tumor cell proliferation via CX3CR1." (PMID 21750716, 2011).
peripheral vascular disease (1 paper, 2013). Any disorder affecting blood flow through the veins or arteries outside of the heart. "Furthermore, expression and secretion of CCL-2, CCL-5 and CX3CL-1 by human coronary artery endothelial cells as well as monocytes was inhibited by preincubation with rHDL, and rHDL (CSL111; 80 mg/kg) infused in patients with peripheral vascular disease decreased CD11b on neutrophils." (PMID 23967171, 2013).
pituitary tumour (1 paper, 2020). "We also observed a negative correlation between microvessel density and the levels of CXCL10 and CX3CL1 released by pituitary tumour cells." (PMID 32946040, 2020).
plasma cell leukemia (1 paper, 2019). An aggressive plasma cell neoplasm characterized by the presence of neoplastic plasma cells in the peripheral blood. "Primary CD138+ cells and HMCLs expressed CX3CL1 mRNA at low levels, with no statistical differences between HD, MGUS, MM, plasma cell leukemia (PCL), and HMCLs." (PMID 30845779, 2019).
prostate tumors (1 paper, 2020). "The actions of the CX3CL1/CX3CR1 axis in prostate tumor metastasis are mediated via induction of EMT and promotion of cell migration." (PMID 32585812, 2020). "Human prostate tumors express CX3CR1, which facilitates their adhesion to bone marrow CX3CL1-expressing endothelial cells as well as osteoblasts, and triggers PI3K/AKT pathway activation." (PMID 32585812, 2020).
pulmonary embolism (1 paper, 2018). The obstruction of the pulmonary artery or one of its branches by an embolus, sometimes associated with infarction of the lung. "Our previous studies have reported that CX3CL1, CX3CR1, and NF-κB are significantly increased after pulmonary embolism, and NF-κB signaling pathway and CX3CL1/CX3CR1 are perhaps directly involved in the whole inflammatory response of pulmonary embolism." (PMID 30671487, 2018).
pulpitis (1 paper, 2024). Inflammation of the dental pulp. "Results suggested that Cur participated in the neuroimmune response associated with pulpitis by inhibiting the expression of CX3CL1 within the pulpitis, thereby suppressing neuroinflammation and pain hypersensitivity." (PMID 40531313, 2024). "CX3CL1 in the TG significantly increased at 72 h after pulpitis induction, reaching a peak at one week and lasting for four weeks." (PMID 40531313, 2024). "After administering Cur by intraperitoneal injection, the expression levels of Toll-like receptor 4 (TLR4), CGRP, glial fibrillary acidic protein (GFAP), fractalkine (CX3CL1), Tumor necrosis factor (TNF-α), and other factors were examined in the TG of pulpitis-induced rats." (PMID 40531313, 2024).
renovascular hypertension (1 paper, 2018). High blood pressure secondary to renal artery stenosis. "The aim of this study was to evaluate systemic AngII, tumor necrosis factor (TNF), and CX3CL1 mediators in a two-kidney one-clip (2K1C) renovascular hypertension model using Wistar rats infected with T. cruzi." (PMID 29590257, 2018). "In this study, we showed that AngII-induced renovascular hypertension up-regulated TNF and CX3CL1 production in T. cruzi-infected rats, thereby further potentiating cardiac inflammation and fibrosis." (PMID 29590257, 2018).
Respiratory tract infection (1 paper, 2025). An infection of the upper or lower respiratory tract. "However, the high percentage of lung focus in that study is in line with our data, suggesting that the measured increase in CX3CL1 might be particularly pronounced due to respiratory tract infection caused by S. aureus." (PMID 41081526, 2025). "Compared with other severely ill non-infectious ICU prospectively enrolled patients or healthy volunteers, we observed on average 10 times higher levels of CX3CL1 in the S. aureus respiratory tract infections group in both lung fluids and plasma, respectively." (PMID 41081526, 2025). "In this study, we found that patients with S. aureus respiratory tract infections had elevated CX3CL1 levels in airway fluid and plasma." (PMID 41081526, 2025). "Notably, compared with the patients with S. aureus respiratory tract infection, many of the patients with S. aureus bloodstream infection had undetectable levels of CX3CL1 (10 out of 23 below LOD)." (PMID 41081526, 2025). "Furthermore, the addition of anti-α-toxin antibody (MEDI4893*) completely mitigated the NP796- and α-toxin-induced CX3CL1 release in the lung model supernatants, suggesting that CX3CL1 released in S. aureus respiratory tract infection is driven by α-toxin." (PMID 41081526, 2025). "Increased levels of CX3CL1 have been reported in infectious and inflammatory diseases, but whether S. aureus respiratory tract infections and α-toxin are associated with CX3CL1 release is not known." (PMID 41081526, 2025). "Next, we compared the levels of CX3CL1 in frozen plasma samples from healthy volunteers and a retrospective cohort of patients with confirmed S. aureus bloodstream infection, without respiratory tract infections." (PMID 41081526, 2025).
rhinitis (1 paper, 2021). An inflammation of the mucous membrane lining the nose, usually associated with nasal discharge. "Consistently, we observed high expression of CX3CL1 in an independent collection of NPC tumours (n = 113) compared to non-cancerous samples (rhinitis, n = 10)." (PMID 33531485, 2021).
schistosomiasis (1 paper, 2022). An infectious disease caused by parasitic trematodes of the genus Schistosoma that colonize human blood vessels and release eggs that can cause granulomatous reactions leading to acute (swimmer's itch or acute schistosomiasis syndrome) or chronic disease. "Increased Cx3cl1 in granulomas has recently been associated with increased levels of Hyaluronic acid (HA) during schistosomiasis." (PMID 36569914, 2022).
skin cancer (1 paper, 2024). "CX3CL1 expression was also detected in other skin cancer types, along with the infiltration of CX3CR1+ macrophages." (PMID 38903497, 2024).
skin cutaneous melanoma (1 paper, 2023). "CX3CL1 was less expressed in the tumor tissues of adrenocortical carcinoma (ACC), KICH, KIRC, and skin cutaneous melanoma (SKCM)." (PMID 37153002, 2023).
soft tissue sarcoma (1 paper, 2021). A malignant neoplasm arising from muscle tissue, adipose tissue, blood vessels, fibrous tissue, or other supportive tissues excluding the bones. "Additionally, the coexpression of CCL2 and CX3CL1 was strongly associated with prognosis of patients with soft tissue sarcoma, particularly female patients." (PMID 34616731, 2021).
spinal cord injury (1 paper, 2017). Penetrating and non-penetrating injuries to the spinal cord resulting from traumatic external forces (e.g., WOUNDS, GUNSHOT; WHIPLASH INJURIES; etc.). "Apart from the role under physiological conditions, the CX3CL1/CX3CR1 axis was implied to have a role in different neuropathologies such as traumatic brain injury (TBI) and spinal cord injury (SCI)." (PMID 26927660, 2017).
staphylococcal pneumonia (1 paper, 2025). Pneumonia caused by infections with bacteria of the genus staphylococcus, usually with staphylococcus aureus. "Using a 3D human in vitro staphylococcal pneumonia model, we show that α-toxin-induced activation of ADAM10 as well as α-toxin-induced cytotoxicity leads to increased CX3CL1 release, which enhances monocyte motility and impairs intracellular killing capacity by monocytes." (PMID 41081526, 2025).
steatosis (1 paper, 2022). Increased lipid within the cytoplasm of cells. "The plasma levels of CX3CL1, TNF, CD40, CSF‐1, and TWEAK were lower in moderate steatosis versus no steatosis." (PMID 35128832, 2022).
tendinopathy (1 paper, 2019). "Given the role in cell proliferation, angiogenesis and fibrosis upon inflammation, and considering that they are hallmarks of tendinopathy, targeting the CX3CL1/CX3CR1/EREG axis could potentially open up new vistas in tendinopathy therapy." (PMID 31744815, 2019).
thyroid tumor (1 paper, 2026). A benign or malignant neoplasm affecting the thyroid gland. "Our findings suggest that miR-1179 is a tumor suppressor gene and that its loss may contribute to thyroid tumor progression by promoting the expression of ELF3, NOTCH3, and CX3CL1." (PMID 42121903, 2026).
Tinnitus (1 paper, 2023). Tinnitus is an auditory perception that can be described as the experience of sound, in the ear or in the head, in the absence of external acoustic stimulation. "Proteins showing significance before correction for association with tinnitus were NT-3, uPA, and CX3CL1 when using the whole sample, and NT-3, CX3CL1, and CCL3 when using discordant twins." (PMID 38079022, 2023). "Before correction, significant constant tinnitus was associated with SCF, TWEAK, and CX3CL1 using the whole TwinsUK sample, and CX3CL1 using the discordant twin pairs." (PMID 38079022, 2023).
transient arthritis (1 paper, 2023). Arthritis that is not permanent. "We also found new biomarkers that correlated with reactogenicity, including transient arthritis (MCP-2, CXCL10, CXCL11, CX3CL1, MCSF, IL-15, OSM)." (PMID 38235127, 2023).
viral meningitis (1 paper, 2019). Inflammation of the membranes surrounding the brain and spinal cord due to a viral infection. "CX3CL1 and CXCL12 were only found elevated in viral meningitis." (PMID 31727097, 2019).
ZIKV infection (1 paper, 2018). "However, the role of CX3CR1 and its ligand CX3CL1 during ZIKV infection and its effect on the interaction between neurons and microglia at the synapse have not been identified yet." (PMID 30359409, 2018).
tumor (280 papers, 2009 to 2026). "Overexpression of CX3CL1 inhibited tumor cell growth and metastasis in ccRCC and promoted tumor susceptibility to ferroptosis." (PMID 40508161, 2025). "Tumor-specific Ythdf2 loss suppresses tumor growth, prolongs survival, recruits macrophages via CX3CL1, reduces glycolysis, enhances CD8+ T-cell mitochondrial respiration, and promotes pro-inflammatory macrophage polarization and antigen presentation." (PMID 41403953, 2025). "In epigenetic studies, CX3CL1 expression levels were closely associated with the level of CD8+ T cell infiltration into the tumor microenvironment (TME)." (PMID 40508161, 2025). "In patients with BCa, positive CX3CL1 expression is significantly associated with advanced tumor stage, larger tumor size, higher grade, and the presence of metastasis." (PMID 39409924, 2024). "When CX3CR1 binds to CX3CL1, multiple pathways are activated that cause tumor and immune cells to migrate, invade, and metastasize, ultimately leading to angiogenesis." (PMID 38433196, 2024). "CX3C motif chemokine receptor 1 (CX3CL1), for example, has been reported to play an anti-tumor role in spinal metastases, but more recent studies have postulated that CX3CL1 expression is associated with a worse prognosis." (PMID 39335124, 2024). "CX3CL1 was robustly associated with clinical characteristics and pathological stages, suggesting that it was related to the degree of tumor malignancy and the physical function of patients." (PMID 37153002, 2023). "Fractalkine/CX3CL1 is similarly involved in the regulation of tumor-associated macrophage infiltration/polarization and the angiogenesis." (PMID 37509362, 2023). "Expression of several other genes upregulated by ruxolitinib such as Csf2, Cx3cl1, Cx3cr1, Has1, and Ccl22 in myeloid cell populations is known to be associated with tumor progression, myeloid cell accumulation, and tumor progression." (PMID 37005447, 2023). "Studies further exhibited that chemokine/receptor pairs like CXCL12/CXCR4/CXCR7, CXCL16/CXCR6, and CX3CL1/CX3CR1 were obviously associated with tumor progression." (PMID 35419058, 2022). "Meanwhile, it suggests that concentrating on the differences in immunotherapy response caused by tumor heterogeneity will help us better understand the clinical applicability of CX3CL1 in ccRCC." (PMID 36397015, 2022). "Multivariable analysis showed that CX3CL1 expression remained significantly associated with tumor size, tumor stage, Ki67 expression, disease recurrence, and mortality (all P<0.05)." (PMID 34671562, 2021). "TGF-β has also a direct effect on NK cells by increasing the expression of miR-27a-5p in these cells, which causes a decrease in CX3CR1 expression, and thus, affects CX3CL1-dependent migration of these cells to the tumor niche." (PMID 32466280, 2020). "While IL-1β and IL-6 have been linked to the generation of MDSC inside tumor tissues, CX3CL1 and CCL22 have been found to induce the recruitment of MDSCs into the tumor microenvironment in tumor-bearing hosts." (PMID 32632113, 2020). "This tumor carried the highest number of somatic mutations herein detected, including CX3CL1 and CTNNB1 mutations, and its chromosome copy number profile was complex compared to the HB group (data not shown)." (PMID 32432034, 2020). "In fact, several studies reported a correlation between CX3CL1 production by tumor cells or tumor-associated cells and a good prognosis." (PMID 32824655, 2020). "Only six tumors presented upregulation of CX3CR1 mRNA, compared to control (fold-change >2, p < 0.05), including a CX3CL1-mutated tumor (HB32)." (PMID 32432034, 2020). "Increased expression of CX3CL1 causes homing of anti-tumor cells of the immune system that express CX3CR1." (PMID 32466280, 2020). "We extensively discuss the importance of CX3CL1 in the interaction with different cells in the tumor niche: tumor-associated macrophages (TAM), myeloid-derived suppressor cells (MDSC) and microglia." (PMID 32466280, 2020).
tumor (continued). "The CX3CL1 variant was validated by target sequencing in both tumors at heterogeneity; however, Sanger sequencing detected the mutation only in the tumor sample with the higher variant frequency (HB33, 40%) but did not detect in additional 47 HB samples." (PMID 32432034, 2020). "This latter was based on the increased CX3CL1 expression on inflamed blood vessels of mouse lung after intravenous injection of tumour cells, as well as some known deficiencies of CX3CR1−/− mice." (PMID 29367702, 2018). "By contrast, PD-L1-deficient tumours exhibited a different array of T-cell chemoattractants (e.g., CX3CL1), and an increase in general inflammatory cytokines, especially those associated with neutrophil/granulocytic MDSC infiltration, for example, CXCL1/3/5." (PMID 28220772, 2017). "The chemokine fractalkine (CX3CL1) has also been implicated in the invasive and metastatic potential of several tumours including lung, ovarian and prostate cancer." (PMID 29157300, 2017). "In prostate cancer and pancreatic ductal adenocarcinoma, cancer metastasis is associated with CX3CR1 on tumor cells and the ligand CX3CL1 at metastasis site." (PMID 25110692, 2014). "They provide further insight into the role of CX3CL1 in malignant cell proliferation and tumor growth, closely associated with GILZ." (PMID 21750716, 2011). "In xenografted mice, the overexpression of both GILZ and CX3CL1 is associated with faster tumor growth." (PMID 21750716, 2011). "Under these conditions, the rate of cell proliferation was markedly decreased, underlying a role for endogenous CX3CL1 in regulating tumor cell proliferation." (PMID 21750716, 2011). "In a mouse subcutaneous xenograft model, the overexpression of GILZ was associated with higher expression of CX3CL1 and faster tumor growth." (PMID 21750716, 2011). "Although CX3CL1 has been linked to anti-tumor immunity, its role in ICT response is undefined." (PMID 41279119, 2025). "CX3CL1 was thus specifically expressed in Vhl-deficient tumors and recruited proinflammatory TAMs that may have promoted tumor growth." (PMID 38618956, 2024). "To evaluate the association between increased CX3CL1 expression in cervical LN metastatic areas and tumor lymphangiogenesis in patients with OSCC, we analyzed and counted PDPN+ structures around OSCC cancer nests in primary tumors representing the invasive front of OSCC." (PMID 38775151, 2024). "Reduced CX3CL1 expression has been associated with enhanced tumor invasion and metastasis." (PMID 38456941, 2024). "In ccRCC, TAMs may support tumor fitness or disease progression, at least in part, by the proinflammatory action of CX3CL1 driven by VHL loss." (PMID 38618956, 2024). "Interestingly, Vhl loss resulted in increased cancer cell production of the cytokine CX3CL1, and deletion of Cx3cl1, together with Vhl, led to slower tumor growth and decreased myeloid infiltration associated with Vhl loss." (PMID 38618956, 2024). "CX3CL1 may also promote the adhesion of CX3CR1-positive tumor cells to target organs, thus causing the migration of tumor cells and promoting tumorigenesis." (PMID 37770496, 2023). "Therefore, a thorough examination of CX3CL1 in cancer is required to determine its association with clinical phenotypic characteristics, tumor prognosis, and tumor immune infiltration." (PMID 37153002, 2023). "Finally, analysis of lymphocyte-associated factors showed that the NK cell-associated cytokine CX3CL1 was downregulated in the tumor diameter ≥3 cm group (Student’s t-test, p = 0.0086)." (PMID 37063892, 2023). "We found that high expression of CX3CL1 was significantly associated with higher risk of disease recurrence and cancer-specific death; through in vivo and in vitro functional study, we further confirmed that high expression of CX3CL1 was associated with tumor cell proliferation and invasion." (PMID 34671562, 2021).